Y_RNA (Y RNA )
Gene: Miscellaneous RNA gene on chromosome 19 (38,294,544 to 38,294,636, forward strand). Ensembl gene ENSG00000200209.
Homologues: Orthologues: chimpanzee Y_RNA (98% identical). Paralogues in human: Y_RNA (84% identical), Y_RNA (83% identical), RNY3 (82% identical), Y_RNA (82% identical), Y_RNA (81% identical), RNY3P1 (80% identical), RNY3P13 (80% identical), RNY3P16 (80% identical), RNY3P4 (80% identical), Y_RNA (80% identical), Y_RNA (78% identical), RNY3P14 (77% identical), and 90 more.